NBPF6 (NBPF member 6)
Tractability: No criterion of Open Targets' tractability assessment is met for any kind of drug.
Gene: Protein-coding gene on chromosome 1 (108,450,282 to 108,471,920, forward strand). Ensembl gene ENSG00000186086.
Subcellular location: Cytoplasm
Subcellular location (Human Protein Atlas): Cytosol; Nucleoplasm
Gene Ontology:
Cellular component: cytoplasm
Genetic constraint (gnomAD): Loss-of-function variants: 2 observed, 4.55 expected, observed/expected ratio (o/e) 0.44, 90% interval 0.18 to 1.35. That is too few expected variants to judge how well the gene tolerates losing a copy. Missense variants: 42 observed, 78.7 expected, observed/expected ratio (o/e) 0.53, 90% interval 0.42 to 0.69. Synonymous variants: 11 observed, 28.41 expected, observed/expected ratio (o/e) 0.39, 90% interval 0.24 to 0.64.
Homologues: Orthologues: macaque NBPF6 (82% identical). Paralogues in human: NBPF4 (99% identical), NBPF12 (47% identical), NBPF19 (47% identical), NBPF14 (47% identical), NBPF20 (47% identical), NBPF8 (47% identical), NBPF10 (46% identical), NBPF26 (46% identical), NBPF9 (46% identical), NBPF3 (45% identical), NBPF15 (43% identical), NBPF11 (43% identical), and 1 more.
Diseases named in the same sentence as NBPF6 in open-access papers:
NBPF6 is named in the same sentence as 1 disease in open-access papers, as found by Europe PMC text mining. Sharing a sentence is not in itself a finding about the gene and the disease. The quoted sentences say what the papers report.
breast carcinoma (1 paper, 2020). "LongGF also detected more potential novel gene fusions (ACTB:H3F3B, SLC25A24:NBPF6, STMN1:ACTG1), and these genes were reported to be associated with breast cancer." (PMID 33372596, 2020).